CFTR (CF transmembrane conductance regulator)
Diseases named in the same sentence as CFTR in open-access papers (continued):
Sharing a sentence is not in itself a finding about the gene and the disease.
colon carcinoma (28 papers, 2012 to 2025). "It has long been known that loss of another epithelial Cl− efflux protein, the Cl− channel CFTR, which is highly expressed in the more distal parts of the GI tract, is associated with a strong increase in the incidence of colon cancer." (PMID 35426084, 2022). "In this ring trial the participants had to comment on two problems: (i) fertility disorder in a man with deletion of the AZFc region and heterozygous mutation in the gene CFTR and (ii) histologically verified colon cancer in the counselee and a positive family history of colon cancer." (PMID 38836209, 2021). "In addition, CFTR is believed to be a tumor suppressor gene and disruption, as in CF, leads to increased risk for colon cancer and other digestive tract cancers." (PMID 33198722, 2020). "We validated the earlier RNA data by examining CFTR protein levels in Capan‐1, NP31 and BxPC‐3 cells by western blot, using the CFTR‐expressing colon carcinoma cell line HT29 as a positive control." (PMID 40785146, 2025). "Our data, while still anecdotal, suggests a need for further investigations of the potential effects of the CFTR modulator medications in the gastrointestinal tract, and their potentially chemoprotective role against colon cancer." (PMID 39133871, 2024). "Endogenous CFTR mRNA is targeted for NMD in human bronchial epithelial cells and colon cancer cells harboring the homozygous CFTR-W1282X mutation (16HBE-W1282X and DLD1-W1282X cells)." (PMID 35624092, 2022). "An interaction between CFTR and tight and adherens junction component AF-6/anadin has also been reported in colon cancer cell lines with a knockdown of CFTR leading to a reduced epithelial tightness and enhanced malignancies." (PMID 34947992, 2021). "IL-1β has recently been reported to stimulate the expression of CFTR in T84 colon carcinoma cells, through NF-κB signalling." (PMID 26594334, 2015). "We have previously shown that IL-1β, at low doses (∼30 pM), can stimulate the expression of CFTR in T84 colon carcinoma cells, through NF-κB signaling." (PMID 24901709, 2014). "For this purpose, T84 and Caco-2 colon carcinoma cells were used; these cells express high levels of CFTR." (PMID 23185247, 2012). "Moreover, another epithelial Cl- channel, CFTR is related to an increased incidence of colon cancer." (PMID 38461207, 2024). "Moreover, β2-AR agonists activate CFTR in intestinal organoids through cAMP signaling, and optimal activity of CFTR in Caco-2 human colon carcinoma cells is dependent on the presence of glucose." (PMID 36699012, 2022). "To investigate whether AAT has any effect on CFTR levels, we first employed human colon carcinoma T84 cell line." (PMID 33946490, 2021). "Robust markers of metaplasia in our study included cathepsin E (CTSE), which has been associated with gastric and colon cancers and previously shown to be upregulated in patients with BAR and EAC, as well as the anion/bicarbonate channel CFTR and PDZ-domain-containing mucins MUC17, MUC3A, and MUC12." (PMID 34412659, 2021). "A similar subcompartmentalised CFTR activation has been proposed for an anti-colon cancer drug (irinotecan) and an anti-retroviral drug (3′-azido-3′-deoxythymidine) using intestinal fluid secretion in closed-loop diarrhoea model and enterospheres, isolated from wild-type (Mrp4+/+) and Mrp4−/− mice." (PMID 31481727, 2019). "Moreover, colon carcinoma T84 and Caco-2 cells, which express wt-CFTR, either treated with CFTR inhibitors (glibenclamide, CFTR(inh)-172 or GlyH101) or transfected with a CFTR-specific shRNAi, showed a significant reduction on the IGA of mCx-I." (PMID 23185247, 2012). "Open chromatin profiles at the CFTR locus in BxPC‐3, Capan‐1 and NP31 cells were generated by ATAC‐seq and compared to well‐characterised open chromatin maps in colon carcinoma (Caco‐2) and lung adenocarcinoma (Calu‐3) cells that we published earlier." (PMID 40785146, 2025).
colon carcinoma (continued). "One such coupling is between CFTR and MRP4 in HT29 colon carcinoma cells, where MRP4 functions as a cAMP transporter." (PMID 25263207, 2014). "CFTR (ABCC7), a member of the ABC super family, has been shown to act as a tumor suppressor in all the GI cancer types in both patients with CF and in sporadic GI cancers as it is one of the most differentially expressed genes in pancreatic and colon cancer." (PMID 35743652, 2022). "This compound inhibited CFTR in vitro with a 50% inhibitory concentration (IC50) of approximately 5 μM (equivalent to 2,725 ng/mL) on Chinese hamster ovary (CHO) cells expressing human CFTR and on T84 colon carcinoma cells." (PMID 34793441, 2021).
liver disease (28 papers, 2010 to 2026). "Nevertheless, our study encompasses a large, national cohort of LT candidates with CFTR and provides valuable insights into a rare but relevant cause of liver disease." (PMID 41362828, 2026). "Usually, it is difficult to discriminate if the liver disorder is related to the underlying CFTR defect or is secondary due to extrahepatic or iatrogenic complications." (PMID 41465734, 2025). "We aimed to investigate the efficacy of CFTR-modulators in CF-associated liver disease (CFLD) during long-term treatment." (PMID 41465734, 2025). "Although cholangiocytes and, to a lesser extent, hepatocytes express CFTR, the pathophysiological basis by which loss of CFTR causes liver disease is poorly understood." (PMID 38743489, 2024). "We reported that CF-9 rabbits (interchangeably referred to as “CF rabbits” hereafter; other CFTR mutation types are specified) exhibit many typical CF phenotypes, such as growth retardation, intestinal obstruction, airway abnormalities, and liver disorders." (PMID 38358827, 2024). "The etiological mechanisms underlying liver disease in the context of CF remain incompletely elucidated, although certain CFTR gene mutations, particularly the F508 del homozygous mutation, are identified as augmenting the risk and severity of manifestation." (PMID 38473009, 2024). "In previous studies, C22:5n-3 concentration reductions correlated with more severe CFTR mutations, worse pulmonary function and CF related liver disease." (PMID 28106773, 2017). "CFTR-deficient neonatal ferrets exhibit similar phenotypic characteristics to humans, including liver disease, pancreatic disease, and spontaneous lung infections." (PMID 27340661, 2016). "The only detectable difference between these 3 groups of patients, based on the CFTR mutation, was the frequency of the liver disease: 36% of the F508del homozygous group had liver disease vs 0% in the 2 other groups." (PMID 21826199, 2011). "We report two cases of Somali siblings with rare CFTR 896delT (c.764del; p.Ile255ThrfsX6; dbSNP rs2485020167; ClinVar ID 2682475; NM_000492.4:c.764del) homozygous variants who manifested classic CF lung and hepatic disease." (PMID 42040987, 2026). "CFTR mutations also affect the hepatobiliary system and liver diseases are risk factors for CFRD." (PMID 34394004, 2021). "Additionally, defects in the CF transmembrane conductance regulator (CFTR) may lead to CF-related liver disease (CFrLD), the third leading cause of death among the CF population." (PMID 41362828, 2026). "Mutations in the CFTR gene result in the accumulation of hyperviscous bile in the biliary tree, leading to hepatocyte and cholangiocyte damage, inflammation, focal fibrosis, and progression to multinodular cirrhosis, portal hypertension, and liver decompensation." (PMID 38473009, 2024). "Advanced liver disease was an exclusion criterion in all clinical trials evaluating CFTR modulators, leaving a critical gap in understanding its effectiveness on CFLD outcomes." (PMID 41070102, 2025). "In conclusion, adults with CF receiving long-term CFTR modulators, showed improvement of liver disease assessed by ultrasonography and transient elastography." (PMID 41465734, 2025). "CFTR is expressed in the biliary epithelium, where dysfunction alters bile secretion and flow, contributing to cholangiopathy and eventually portal hypertension." (PMID 41070102, 2025). "In conclusion, this long-term, real-world study of adults receiving CFTR modulators showed improvement of liver disease assessed by ultrasonography and transient elastography." (PMID 41465734, 2025). "The scarce correlation between the CFTR genotype and liver expression in CF patients is well known, as it is the discordant severity of liver disease in CF sib pairs." (PMID 25132997, 2014). "Therefore, checking AAT before starting CFTR modulator therapy can be suggested, in particular for children with previous, even transient, liver disease." (PMID 38655277, 2024).
liver disease (continued). "While no specific CFTR mutations have been consistently linked to liver disease severity, environmental and genetic modifiers, such as the SERPINA1 Z allele, may play an important role in disease development." (PMID 41527672, 2026). "Despite CFTR dysfunction affecting all patients, severe liver disease develops selectively, irrespective of genotype, implying the involvement of additional factors in its pathogenesis." (PMID 38473009, 2024). "Although the biliary phenotype of CFLD could plausibly respond to CFTR modulation, the vascular subtype, characterized by non-cirrhotic portal hypertension, has an uncertain pathogenesis and its response to ETI is unknown." (PMID 41070102, 2025). "Our findings support the view that individuals with chronically established liver disease may not completely respond to CFTR modulators even after long-term treatment." (PMID 41465734, 2025). "Through blood analyses the liver function of CFTR−/− ferret kits demonstrated low levels of cholesterol and high levels of plasma alanine aminotransferase (ALT) and bilirubin, which highlights an early onset of liver disease, although no liver lesions were found in CFTR−/− ferrets." (PMID 27340661, 2016).
metabolic syndrome (27 papers, 2015 to 2025). A cluster of metabolic risk factors for CARDIOVASCULAR DISEASES and TYPE 2 DIABETES MELLITUS. "As pwCF taking CFTR modulators age, c‐morbidities associated with advanced age, such as cardiovascular disease, dyslipidemia, and malignancies, are becoming more common." (PMID 40533897, 2025). "The 7T allele is associated with CFTR-Related Metabolic Syndrome, while the 9T and 11T alleles are rarely problematic." (PMID 38611676, 2024). "One had variant combination that was reported to cause CF but all were diagnosed with CFTR-related metabolic syndrome." (PMID 29326970, 2018). "CFTR misfunction in CF is associated with altered lipid homeostasis, consisting in inflammatory ceramide accumulation in the lung, sterol accumulation in the airways, hepatic steatosis, and plasma dyslipidemia." (PMID 32408521, 2020). "This inconclusive outcome has been termed CF transmembrane conductance regulator (CFTR) related metabolic syndrome (CRMS) or CF screen positive, inconclusive diagnosis (CRMS or CFSPID)." (PMID 40053726, 2025). "Of these, 51 newborns were diagnosed with CF, 21 had CFTR-related metabolic syndrome, and 489 were CF carriers (66% had an F508del-CFTR)." (PMID 36986509, 2023). "We compared the psychological impact of CF transmembrane conductance regulator-related metabolic syndrome (CRMS)/CF screen-positive, inconclusive diagnosis (CFSPID), and clear CF diagnosis, on parents." (PMID 36832306, 2023). "In comparison to ETI-exposed newborns, all these groups exhibited higher mean levels of immunoreactive trypsinogen: 191.6 ng/mL in newborns with CF, 96.7 ng/mL in those with CFTR-related metabolic syndrome, and 66.9 ng/mL in CF carriers." (PMID 36986509, 2023). "Infants with abnormal CF screening results and inconclusive confirmatory testing results are referred to as having “CFTR-related metabolic syndrome” or CF screen positive, inconclusive diagnosis” (CFSPID)." (PMID 26702401, 2015). "We hypothesized that ETI-exposed infants have lower IRT values than newborns with CF, CFTR-related metabolic syndrome/CF screen positive, inconclusive diagnosis (CRMS/CFSPID), or CF carriers." (PMID 36975847, 2023). "We hypothesized that infants born to mothers with CF taking ETI (ETI-exposed) while pregnant may have lower concentrations of IRT than newborns with CF, CFTR-related metabolic syndrome/CF screen positive, inconclusive diagnosis (CRMS/CFSPID), or CF carriers." (PMID 36975847, 2023). "However, identification of infants with an inconclusive diagnosis after a positive NBS result—termed cystic fibrosis transmembrane conductance regulator (CFTR)-related metabolic syndrome or CF Screen Positive Inconclusive Diagnosis (CRMS/CFSPID) is an increasingly recognized outcome." (PMID 35076474, 2022).
COVID-19 (26 papers, 2020 to 2025). A disease caused by infection with severe acute respiratory syndrome coronavirus 2. "Specifically, individuals carrying single pathogenic versions of the CFTR gene (CF vendors) are more susceptible to respiratory tract infections and severe COVID-19." (PMID 38694803, 2024). "Conversely, subjects carrying single pathogenic variants of the CFTR gene, i.e. CF carriers, more likely underwent severe COVID-19 with high risk of 14-day mortality." (PMID 37957647, 2023). "Nonetheless, our study shed light on the incidence and clinical course of COVID-19 in children with CF with CFTR I1234V mutation that is distinctive to our region." (PMID 38089672, 2023). "The distribution of the gain-of-function and loss-of-function CFTR alleles among the COVID-19 clinical categories showed an age- and sex-dependent pattern." (PMID 36552859, 2022). "Carriers of single pathogenic variants of the CFTR (cystic fibrosis transmembrane conductance regulator) gene have a higher risk of severe COVID-19 and 14-day death." (PMID 36552859, 2022). "Among the low-frequency variants extracted, we identified some genes associated with either severity or protection from severe COVID-19 that are linked to the CFTR pathway (e.g., PSMA6) as well as specific genes involved in the immune response (e.g., NOD2)." (PMID 34889978, 2022). "In conclusion, CFTR genetic analysis is an important tool in identifying patients at risk of severe COVID-19." (PMID 36552859, 2022). "Thus, the accurate genetic analysis of CFTR is an important tool for identifying patients at risk of severe COVID-19." (PMID 38203285, 2023). "Thus, it might be reasonable to consider whether loss of CFTR function could contribute in some way to COVID-19." (PMID 39043712, 2024). "This study presents a novel description of the SARS-CoV-2 cell cycle in human bronchial epithelial cells, with and without CFTR-modification, and could pave the way to a better understanding of the impact of COVID-19 on pwCF by characterizing SARS-CoV-2 infection in ΔF-mutated CFTR cells." (PMID 36077122, 2022). "Therefore, we hypothesized that the overall activity of CFTR, determined mainly by the genetic variants that each individual carries, could be a prognostic factor influencing COVID-19 severity." (PMID 36552859, 2022). "As part of this national effort, we conducted the present study, under the hypothesis that a subset of individuals carrying single pathogenic variants of the cystic fibrosis transmembrane conductance regulator (CFTR) gene is more susceptible to the most critical form of COVID-19." (PMID 34203982, 2021). "These evidences link inversely the degree of expression of the CFTR channel and COVID-19 severity, pointing to a molecular biological plausibility corroborating the role of CFTR in the pathogenesis of SARS-CoV-2 infection." (PMID 37957647, 2023). "This intriguing observation on the peculiarity of SARS-CoV-2 infection in pwCF prompts the investigation of the role of CFTR channel functions in COVID-19 pathophysiology." (PMID 37957647, 2023). "In conclusion, our work highlights the importance of the CFTR genetic profile in determining COVID-19 presentation and progression, opening new perspectives in personalized approaches for COVID-19." (PMID 36552859, 2022). "Here, we demonstrate that the global impairment of CFTR function, either by a strong LOF allele in heterozygosity or compound heterozygosity for two hypomorphic alleles, is associated with COVID-19 severity." (PMID 36552859, 2022). "The machine learning post-Mendelian model pinpointed CFTR as a bidirectional modulator of COVID-19 outcomes." (PMID 36552859, 2022). "We propose initiating treatment immediately upon hospital admission, since CFTR dysfunction is likely an early and persistent aspect of the COVID-19 disease progression and therefore likely to be present at the time of diagnosis." (PMID 33250777, 2020).